MRGPRX3 (MAS related GPR family member X3)
Description:
Orphan receptor. Probably involved in the function of nociceptive neurons. May regulate nociceptor function and/or development, including the sensation or modulation of pain. Potently activated by enkephalins (By similarity).
Synonyms: MRGX3; SNSR1; SNSR2; GPCR
Tractability: Small molecule: it belongs to a druggable protein family. Antibody: UniProt places it where antibodies can reach, with medium confidence; UniProt predicts a signal peptide or a membrane-spanning region; its Gene Ontology location is reachable by antibodies, with medium confidence.
Target class: Family A G protein-coupled receptor; Membrane receptor
Gene: Protein-coding gene on chromosome 11 (18,120,955 to 18,138,488, forward strand). Ensembl gene ENSG00000179826.
Subcellular location: Cell membrane
Gene Ontology:
Molecular function: protein binding; G protein-coupled receptor activity; transmembrane signaling receptor activity
Biological process: G protein-coupled receptor signaling pathway; adenylate cyclase-modulating G protein-coupled receptor signaling pathway; phospholipase C-activating G protein-coupled receptor signaling pathway
Cellular component: plasma membrane; membrane
Genetic constraint (gnomAD): Loss-of-function variants: 14 observed, 16.62 expected, observed/expected ratio (o/e) 0.84, 90% interval 0.56 to 1.32. The upper end of that interval is the gene's LOEUF score, 1.32, which puts it in group 5 of 6, group 1 being the genes least tolerant of losing a copy. Missense variants: 330 observed, 330.9 expected, observed/expected ratio (o/e) 1, 90% interval 0.91 to 1.09. Synonymous variants: 157 observed, 143.03 expected, observed/expected ratio (o/e) 1.1, 90% interval 0.96 to 1.25.
Homologues: Orthologues: chimpanzee MRGPRX3 (96% identical), macaque MRGPRX3 (90% identical), rabbit MGRG2 (55% identical), dog MRGPRX (53% identical), rat Mrgprx3 (52% identical), mouse Mrgprx1 (51% identical), rat Mrgprx1 (51% identical), mouse Mrgpra9 (50% identical), mouse Mrgpra1 (50% identical), mouse Mrgpra3 (50% identical), mouse Mrgprx2 (50% identical), mouse Mrgprb2 (48% identical), and 16 more. Paralogues in human: MRGPRX1 (83% identical), MRGPRX4 (82% identical), MRGPRX2 (64% identical), MRGPRD (37% identical), MAS1L (33% identical), MAS1 (31% identical), MRGPRF (31% identical), MRGPRE (30% identical), MRGPRG (28% identical), GPR152 (21% identical).
Diseases named in the same sentence as MRGPRX3 in open-access papers:
MRGPRX3 is named in the same sentence as 2 diseases in open-access papers, as found by Europe PMC text mining. Sharing a sentence is not in itself a finding about the gene and the disease.
MRGPRX3 shares sentences with these, for which no sentence is quoted: bacterial infection (1 paper); Stroke (1).